CCL2 (C-C motif chemokine ligand 2)
Diseases named in the same sentence as CCL2 in open-access papers (continued):
Sharing a sentence is not in itself a finding about the gene and the disease.
progeria (4 papers, 2020 to 2025). "To investigate the prosenescence effects of Ccl2 in accelerated aging at the organismal level, we developed an experimental model that combines progeria induced by a mutation in the Lmna gene and systemic Ccl2 overexpression." (PMID 33104522, 2020). "Taken together, our data indicate that Ccl2 overexpression in the experimental model of progeria alters energy and 1-C metabolism and drives dynamic changes in DNA methylation." (PMID 33104522, 2020). "It was noticeable that progeria and Ccl2 overexpression increased methionine levels in the muscles and altered the DNA methylation status, likely with associated epigenetic changes." (PMID 33104522, 2020). "ACKR4 is also among the CCL2-related DEGs that progeria and aging have in common." (PMID 36289702, 2022). "Therefore, we visualized the interactions of CCL2 and the CCL2-related DEGs involved in both aging and progeria." (PMID 36289702, 2022). "Circulating CCL2 levels increased in an age-dependent manner in wild-type mice, and that age-dependent increase was accelerated in Ercc1−/Δ and Bubr1H/H mouse models of progeria." (PMID 35218410, 2022). "The results indicated that excessive Ccl2 promoted the death of the mice with progeria." (PMID 33104522, 2020). "Many genes, such as CCL2 and UCP2, were upregulated in progeria whilst CD27, CD28, and TIGIT were dysregulated in senescent cells." (PMID 40343591, 2025). "To find possible interaction partners of CCL2 that are differentially expressed in both analyses, we uploaded the set of HGPS DEGs obtained by comparing progeria patients and healthy children in STRING." (PMID 36289702, 2022). "Although CCL2 levels are higher in progeria patients than in nonagenarians, both nonagenarians and progeria patients have higher CCL2 levels than healthy children." (PMID 36289702, 2022). "When comparing CCL2 expression in progeria patients and nonagenarians, CCL2 is more expressed in progeria." (PMID 36289702, 2022). "In both analyses, aging and progeria, IGF1 and CCL2 are among the prioritized ligands." (PMID 36289702, 2022). "ACKR4 has been mentioned as a receptor for CCL2 which is upregulated in nonagenarians compared to healthy children in our study, whereas the ACKR4 expression in progeria is very low in all comparisons." (PMID 36289702, 2022).
retinoblastoma (4 papers, 2020 to 2025). A malignant tumor that originates in the nuclear layer of the retina. "Specifically, in retinoblastoma-deficient tumors, CCL2 expression is upregulated through the activation of AMP-activated protein kinase (AMPK)." (PMID 37469162, 2024). "Increased CCL2 secretion was also found in the protumoral microenvironment induced by retinoblastoma inactivation." (PMID 32986377, 2020).
Sjögren’s syndrome (4 papers, 2019 to 2025). "CCL2 protein levels, quantified by enzyme-linked immunosorbent assay (ELISA) in sera samples from pSS patients, correlated with the European Alliance of Associations for Rheumatology’s Sjogren’s syndrome disease activity index (ESSDAI) score for systemic activity." (PMID 38255988, 2024).
spinal cord injury (4 papers, 2016 to 2024). Penetrating and non-penetrating injuries to the spinal cord resulting from traumatic external forces (e.g., WOUNDS, GUNSHOT; WHIPLASH INJURIES; etc.). "After spinal cord injury (SCI) activated astrocytes release C-C Motif Chemokine Ligand 2 (CCL2), which binds to C-C motif receptor 2 (CCR2) to induce microglia activation and neuronal apoptosis." (PMID 37728588, 2024).
thyroid (4 papers, 2020 to 2026). "The study of the tumor microenvironment (TME) showed that thyroid tumoral tissues overexpress CSF-1 and CCL-2 that attract tumor associated macrophages (TAMs)." (PMID 32668761, 2020). "CCL2, a chemokine secreted by PTC cells, facilitates TAM recruitment in thyroid TME." (PMID 32982967, 2020).
trigeminal neuralgia (4 papers, 2012 to 2024). Trigeminal neuralgia is a nerve disorder that causes a stabbing or electric-shock-like pain in parts of the face. "Targeting the CCL2/CCR2 pathway may provide a novel therapeutic approach for the treatment of the trigeminal neuralgia." (PMID 22721162, 2012). "In the present study patients with trigeminal neuralgia showed lower levels of growth factor levels such as Ang-2, bFGF, HGF, SCF, TGF-α, and VEGF and higher cytokine levels of IL-1β, TNF-α, CCL2, IL-17A, IL-6, and CXCL8 in comparison with normal individuals." (PMID 34067581, 2021).
urticaria (4 papers, 2017 to 2025). A vascular reaction of the skin characterized by erythema and wheal formation due to localized increase of vascular permeability. "For example, CCL5/RANTES, CCL2/MCP-1, and CXCL8/IL-8 are able to induce histamine and serotonin release by mast cells, suggesting their contribution to the development of urticaria by a direct effect on mast cell degranulation." (PMID 29038618, 2017).
vivax malaria (4 papers, 2017 to 2024). "In the present study, vivax malaria patients have shown significant low RANTES/CCL5 levels, but just weakly associated with IL-6, IL-12p40, IFN-γ or MCP-1/CCL2." (PMID 28118834, 2017). "When compared to symptomatic vivax malaria patients, coinfected individuals presented elevated levels of IFN-γ, IL-10 and CCL2, and diminished plasma concentrations of multiple variables as TNF-α, IL-6, IL-12, and CRP." (PMID 31233500, 2019).
Acute encephalopathy (3 papers, 2019 to 2023). "In the children with deadly acute encephalopathy associated with IAV, high concentrations of CCL-2 and CSF have been reported." (PMID 31791311, 2019).
anaplastic astrocytoma (3 papers, 2019 to 2020). "It was revealed that CCL2 is highly expressed in anaplastic astrocytoma and GBM, whereas in fibrillary astrocytoma grade II it is present in lower levels." (PMID 32456359, 2020). "In another study, the serum levels of CCL2 and CCL5 were also increased in anaplastic astrocytoma and GBM patients, at both mRNA and protein levels." (PMID 32456359, 2020).
atrophic gastritis (3 papers, 2020 to 2025). "In extensive atrophic gastritis, the expression of CCL2 and CCL19 was correlated with the infiltration of central memory CD4 T cell, and CD56dim natural killer cell was associated with IL33 expression." (PMID 33426088, 2020). "In an atrophic gastritis environment, the expression of CXCL14, CCL4, CCL26, CCL21, CCL2, CCL19, and CCL13 was correlated with the infiltration of central memory CD4 T cell." (PMID 33426088, 2020).
autoimmune thyroiditis (3 papers, 2012 to 2025). "Additional chemokines, such as CXCL10, CXCL9, CCL2, and CCL22, are expressed in both psoriatic and thyroid autoimmune diseases." (PMID 40863211, 2025).
autoimmune uveitis (3 papers, 2015 to 2022). An autoimmune form of uveitis (disease). "Reduced intensity of autoimmune uveitis with reduced infiltration of T cells, as well as reduced effects of CCL2 and CCL21, chemo-attractive factors for inflammatory cells, were established in their studies." (PMID 35986305, 2022).
benign breast tumors (3 papers, 2018 to 2023). "The concentrations of CCL2 and CA 15-3 in the group of BC were significantly higher than in the benign breast tumors (p<0.001)." (PMID 30151375, 2018). "The CCL2 ELISA data showed that plasma levels of CCL2 were significantly increased in the entire BC group compared to the total control group (benign breast tumor and healthy subjects) (p<0.001), similarly as the median levels of CA 15-3 (p<0.001)." (PMID 30151375, 2018). "We also observed that the median of CCL2 and commonly accepted tumor marker (CA 15-3) levels in all stages of BC were significantly higher when compared to benign breast tumors." (PMID 30151375, 2018). "In BC patients, increased CCL2 serum levels were correlated with advanced tumor stage (p = 0.04) and lymph node involvement (p = 0.04), but serum CCL2 levels could not be established as a differentiation marker between malignant and benign breast tumors." (PMID 37208442, 2023). "We also noticed statistical differences between the concentrations of CCL2 and CCR2 in patients with benign breast tumors and healthy controls (p<0.05)." (PMID 30151375, 2018). "This demonstrates possible chance of using CCL2 and CCR2 in differentiation between benign breast tumor and healthy women." (PMID 30151375, 2018). "Additionally, CCL2 and CCR2 levels may be useful in differentiation between benign breast tumor and healthy women." (PMID 30151375, 2018).
benign prostatic hyperplasia (3 papers, 2005 to 2024). A non-cancerous nodular enlargement of the prostate gland. "First, we compared these measurements to CCL2 concentration in patients with benign prostatic hyperplasia (BPH) (n = 20) and with normal noncancer serum (n = 386)." (PMID 39199567, 2024).
choroidal neovascularization (3 papers, 2012 to 2015). An eye disorder described by the growth of new blood vessels that originate from the choroid through a break in the Bruch membrane into the sub–retinal pigment epithelium (sub-RPE) or subretinal space. "Moreover, studies in experimental laser-induced choroidal neovascularization (CNV) have shown that ablation of either Ccl2 or the receptor Ccr2 inhibits the infiltration of monocytes/microglia and reduces lesion size following CNV." (PMID 22992301, 2012).
chronic lymphocytic leukemia (3 papers, 2019 to 2021). "Similar results have been observed in patients with chronic lymphocytic leukemia, which suggests that the CCL2 is associated with the persistence of leukemic cells." (PMID 34646761, 2021).
chronic myeloid leukemia (3 papers, 2015 to 2021). "The significantly enriched pathways included chemokine signaling pathway (which involved CCL2), focal adhesion (which involved THBS1 and THBS2), TGF-beta signaling pathway (which involved THBS1, THBS2, SMAD5, and SMAD6) and chronic myeloid leukemia (which involved TGFBR2 and CCND1)." (PMID 27716259, 2016).
colorectal adenoma (3 papers, 2015 to 2021). An adenoma that arises from the colon or rectum. "It is established that human colorectal adenomas and CRCs have elevated levels of CCL2 protein, which is localized to cancer cells, consistent with the production of CCL2 by human CRC cells in vitro." (PMID 27058904, 2016). "Therefore, to verify the effect of the polyp sublocation on chemokine expression and discern the independent predictors of CCL2, CCL7, and CCL8 expression in colorectal adenomas, a multivariate analysis was conducted." (PMID 34884259, 2021). "However, data on MCP-1/CCL2 expression in colorectal adenomas are limited, not allowing confirmation of the chemokine potential as a target for chemoprevention." (PMID 34884259, 2021).
corneal infection (3 papers, 2017 to 2024). A viral or bacterial infectious process affecting the cornea. "In a mouse model of Pseudomonas aeruginosa-induced corneal infection, antibodies directed against CCL2 or CCL3 significantly reduced neutrophil infiltration into the cornea and decreased corneal damage." (PMID 29661181, 2018). "MCP-1 also known as chemokine (C-C motif) ligand 2 (CCL2) is one of the critical regulators for leukocyte recruitment during cornea infection." (PMID 28706958, 2017).
coronary artery stenosis (3 papers, 2017 to 2021). "The other study found that elevated levels of sCD163, sCD14, and CCL2 (monocyte chemoattractant protein 1) were associated with greater prevalence of coronary artery stenosis." (PMID 31769428, 2019).
encephalomyelitis (3 papers, 2014 to 2024). Inflammation of the brain and the spinal cord. "Major histocompatibility complex (MHC) II-dependent antigen presentation, CXCL10- and CCL2-mediated recruitment of T cells and macrophages, respectively, are required for fibrinogen-induced encephalomyelitis." (PMID 26353940, 2015). "In addition, CCL2 can supplement T-cell activation-3/CCL1, the ligand of the CCR8 receptor, to guide the infiltration of T cells in encephalomyelitis." (PMID 25009636, 2014).
extra pulmonary tuberculosis (3 papers, 2005 to 2011). "Mycobacterium-induced CCL2 and TNFα, and LPS-induced TNFα responses were greater in pulmonary as compared with extra-pulmonary tuberculosis." (PMID 16001981, 2005). "Reduced CCL2 concomitant with lowered TNFα in extra-pulmonary tuberculosis may lead to lowered protective cellular responses and increased dissemination in these patients." (PMID 16001981, 2005).
Farber disease (3 papers, 2013 to 2025). "Additionally, increased plasma levels of IL6, IL10, IL12, CCL2, CCL3, CXCL1, and VEGF and substantial central nervous system defects have been observed in patients with Farber disease." (PMID 37189685, 2023).
Flavivirus Infections (3 papers, 2018 to 2022). Infections with viruses of the genus FLAVIVIRUS, family FLAVIVIRIDAE. "In particular, CCL2 (MCP-1), induced by flavivirus infection in various cells, could drive the recruitment of bone marrow-derived CCR2hi inflammatory monocytes into the CNS in neuronal infection, as it does in other flavivirus models, to promote immunopathology." (PMID 32375993, 2020).
gastric tumor (3 papers, 2014 to 2025). "In animal gastric tumor models, it was found that macrophage infiltration was induced by CCL2 transfection, but inhibited by anti-CCL2 neutralizing antibody treatment." (PMID 24416340, 2014). "To evaluate whether Wnt5a was engaged in macrophage chemotacxis, we investigated the effect of Wnt5a on the expression of CCL2 which was involved in macrophage recruitment in gastric tumor." (PMID 24416340, 2014). "Through an unbiased integrated analysis of gastric tumor grade and stage, we identified a subset of proangiogenic CAFs characterized by high podoplanin (PDPN) expression, which are significantly enriched in metastatic lesions and secrete chemokine (CC‐motif) ligand 2 (CCL2)." (PMID 39764562, 2025). "The expression of PTGS2, BCL2, and IL7 (inversely) was independently associated with CCL2 in non-cancerous tissue, explaining 88% in gene variability, and HIF1A and BCL2 were independently associated with CCL2 in gastric tumors, explaining 83% in its variation." (PMID 32630408, 2020).
Giardia infection (3 papers, 2011 to 2021). "More research is required in order to determine how Giardia infections may modulate CCL2 and IL-12p70 expression in the context of intestinal inflammatory responses." (PMID 25289678, 2014). "Conversely, CCL2, IL-6, LIF, and IL-12p70 levels in Giardia GS/M-infected animals treated with TcdAB were not significantly different from animals given TcdAB without giardiasis." (PMID 25289678, 2014).
Graves ophthalmopathy (3 papers, 2012 to 2021). An autoimmune disorder of the EYE, occurring in patients with Graves disease. "Also, evidence indicates CCL2 and CXCL10 chemokine modulations by cytokines and PPARγ agonist in Graves’ ophthalmopathy." (PMID 34054797, 2021). "Also, evidence indicated that CCL2 and CXCL10 chemokines, modulated by cytokines and PPARγ agonist, play an important role in Graves’ ophthalmopathy." (PMID 35242125, 2021).
hantavirus infection (3 papers, 2011 to 2023). "Analyzing the immune response, elevated concentrations of specific chemokines (CCL2 and CXCL9) were detected, suggesting their role in the immunopathogenesis of severe hantavirus infections." (PMID 38138107, 2023).
heartburn (3 papers, 2016 to 2025). "The involvement of CCL2 in inflammatory and neurodegenerative diseases and functional dyspepsia point to the involvement of the miR-325-5p/CCL2 signalling in chronic visceral pain in IBS patients and other patients with the gastrointestinal disorder as well." (PMID 37160449, 2023).
hepatic granuloma (3 papers, 2014 to 2020). A granuloma located in the liver. "We found that this sensor influences the formation of hepatic granuloma, altering local chemokine (CCL2, CCL3, and CXCL1) and cytokine (IL-5, IL-10, and IL-13) production, macrophage and neutrophil recruitment into the liver, and also is important for promoting collagen deposition." (PMID 32431709, 2020).
hepatitis B (3 papers, 2013 to 2021). "Topological analysis indicated that AKT1, FOS, CCL2, CXCL8, and CXCL10 are hub genes; TLR signaling pathway, cellular senescence, hepatitis B, and chemokine signaling pathway are key pathways in the IGP network." (PMID 33623529, 2021). "We identified quercetin acted on the targets (AKT1, FOS, CCL2, and CXCL8) through key signal pathways (toll-like receptor signal pathway, hepatitis B, cell senescence, and chemokine signaling pathway) to exert treatment effects on CHB by use of a network pharmacological method." (PMID 33623529, 2021).
herpes zoster (3 papers, 2019 to 2024). A common dermal and neurologic disorder caused by reactivation of the varicella-zoster virus that has remained dormant within dorsal root ganglia, often for decades, after the patient's initial exposure to the virus in the form of varicella (chickenpox). "As observed in ganglion neurons of zoster patients, VZV infection elicits dramatic changes in the DRG xenograft cytokine milieu, including increased production of cytokines associated with neuroinflammatory responses (MCP-1/CCL2, IL-1α, RANTES and IP10/CXCL10)." (PMID 31159224, 2019).
hydronephrosis (3 papers, 2014 to 2023). Collection of urine in the renal pelvis that results in dilatation of the renal pelvis and calyces. "In this regard, chemokines like CCL2/MCP-1, CCL5/RANTES, macrophage inflammatory protein-2 (CXCL2/MIP-2), and γ-interferon-inducible protein (CXCL10/IP-10) have been evaluated in experimental hydronephrosis." (PMID 24692841, 2014).
hyperferritinemia (3 papers, 2015 to 2023). "MCP-1/CCL2 and hyperferritinemia showed direct causal association with depressed ex vivo whole blood TNF response to endotoxin." (PMID 37674218, 2023). "Causal associations of increasing hyperferritinemia category and MCP-1 / CCL2 levels with death and reduced whole blood ex vivo TNF response remained with the addition of preexisting immunocompromise status to the DAG." (PMID 37674218, 2023). "Increased IL-8, IL-18BP, and sCD163 levels were causally associated with MAS; increased IL-8, MIP-1 alpha, M-CSF, and sCD25/IL-2Ra levels were causally associated with increased MCP-1/CCL2 levels; and increased IL-18BP and sCD163 levels were causally associated with hyperferritinemia." (PMID 37674218, 2023). "Monocyte chemoattractant protein 1 (MCP-1)/CCL 2, MAS, and hyperferritinemia were identified as the only three variables directly causally associated with death." (PMID 37674218, 2023). "Among the 41 identified causal nodes, only increased MCP-1/CCL2, MAS, and hyperferritinemia levels were directly causally associated with death." (PMID 37674218, 2023). "Increased MCP-1/CCL2 levels were also causally associated with increased MAS, hyperferritinemia, and sCD163 levels but decreased whole blood ex vivo TNF response to endotoxin." (PMID 37674218, 2023). "Our DAG analysis further identified causal associations between IL-18BP, sCD163, M-CSF, IL-8, MIP-1 alpha, and IL-2Ra/sCD25 with increased MCP-1/CCL2, MAS, and hyperferritinemia." (PMID 37674218, 2023). "However, visualization of the causal pathways with third factor analysis in the DAG implies that therapies which target MCP-1/CCL2, MAS, and hyperferritinemia all together will be more efficacious than therapies that target any one of these alone." (PMID 37674218, 2023).